IL4 (interleukin 4)
Diseases named in the same sentence as IL4 in open-access papers (continued):
Sharing a sentence is not in itself a finding about the gene and the disease.
infection (continued). "M3R deficient mice are highly susceptible to secondary infection, with a 4-fold higher recovery of parasites on day 2 p.i., lower levels of IL-4 and IL-13 in the lungs and reduced goblet cell hyperplasia in the airways." (PMID 25629518, 2015). "Systemic TH2 cytokines were positively associated to infection intensity only in the oldest age group (IL-4: r = 0.488, p = 0.008; IL-5: r = 0.400, p = 0.027; IL-13: r = 0.497, p = 0.007)." (PMID 25799270, 2015). "In L. major, susceptibility to infection is related with the Th1/Th2 balance, and in particular IL-4 expression has been implicated as playing a role." (PMID 24428931, 2014). "Recent studies demonstrate that exacerbated Th2 responses help resistance to L. major in Th1-biased B6 model and that late treatment with anti-IL-4 (2–4 wks) increases susceptibility to infection." (PMID 25110400, 2014). "In contrast, depending on the mouse strain used, the route of infection, the size of the inoculum, and the strain of C. neoformans IL-4 deficiency was found to lead either to increased or reduced survival times." (PMID 24475277, 2014). "Conversely, a Th2 response is associated with susceptibility to infection which is driven by high IL-4, and IL-13 and reduced intracellular parasite killing due to increased Arginase-1 activity." (PMID 24801628, 2014). "The induction of prototypical Th2 response with high IL-4, IL-5 and IL-13 secretion has long been considered to be the hallmark of active infection in human LF." (PMID 24498448, 2014). "Infection of IL-4-deficient mice with Candida albicans results in impaired development of Th1 immunity." (PMID 25126585, 2014). "Because LysMCre-mediated deletion of the floxed IL-4Rα gene is relatively inefficient 57 we predicted that chronic IL-4 exposure was causing an outgrowth of IL-4Rα sufficient macrophages, such that by day 60 post infection all macrophages were wildtype." (PMID 25319331, 2014). "Failure to resolve infection was associated with reduced production of Th2 cytokines, particularly IL-13 and IL-4, abrogated humoral immunity and failure to expand the memory CD4+ T cell compartment." (PMID 24516382, 2014). "IL-4 is produced in the late stages of infection in BALB/C mice and is linked to an increase in pathology in this strain." (PMID 24572168, 2014). "Although the helminth infection-induced immune effector response normally associated with IL-4 is the production of IgE antibody, the Trichinella spiralis experimental infection model is the only one to show a requirement for IgE in protection." (PMID 25360134, 2014). "Neutralization of IL-4 or infection of IL-4-deficient or IL-4R-deficient mice leads to decreased TH2-type cytokine production and prolonged TH1 responses." (PMID 23429492, 2013). "We observed that PBS-pretreated IL-4-/- mice were susceptible to infection, while STAg-pretreated IL-4-/- mice showed resistance." (PMID 24086456, 2013). "Previous infection studies with VV-HA-IL-4 or recombinant ectromelia virus encoding IL-4 suggested that IL-4 dampened the effector function capacity of anti-viral CD8+ T cells and enhanced viral pathogenesis." (PMID 23383283, 2013). "The same group also showed that infections of IL-10/IL-4 and IL-10/IL-12 double deficient mice in comparison to mice with singular deficiencies led to severe immune polarizations to TH1 and TH2, respectively." (PMID 23429492, 2013). "A study on P. knowelsi-inoculated olive baboons reported association between increased levels of IL-4, IL-10, IgM and IgG with increased protection against knowlesi-infection." (PMID 24354660, 2013). "Both BALB/c and C57BL/6 mice secrete IL-4 early after infection however, production of IL-4 is sustained in susceptible BALB/c mice and transient in resistant C57BL/6 mice." (PMID 24204259, 2013). "CD4+ cells, numbers of which significantly increase in the skin after challenge infections, are potential sources of IL-4 associated with Th2 response." (PMID 23125918, 2012).
infection (continued). "Production of interleukin-4 (IL-4) in Leishmania major infection, regulatory T cells in L. mexicana infection, and IL-10 in infection of various species are all associated with susceptibility." (PMID 22448168, 2012). "Elevated IL-4 levels during the late phase of L. major infection in resistant C57BL/6 mice were associated with the maintenance of an existing protection, whereas susceptible BALB/c mice showed elevated IL-4 levels only during the early phase of infection." (PMID 22802978, 2012). "The susceptibility of both monocyte subsets to infection was increased after IL-4 treatment, but this increase was more profound for the CD16+ monocyte subset, particularly at early time points after virus exposure." (PMID 22574162, 2012). "For example, segregation analysis of a Brazilian population has revealed that susceptibility to infection is controlled by the SM1 (S. mansoni 1) gene locus that has been linked to the 5q31–q33 chromosome region comprising the genes for IL-4, IL-5, and IL-13." (PMID 22545160, 2012). "RSV disease and early age of infection are independently associated with a Th2-type cytokine response, hallmarked by increased IL-4 and/or reduced IFNγ production." (PMID 22792355, 2012). "Nevertheless, analysis of the skin-infection site demonstrated thatmultiple exposures to cercariae caused dramatically increased levels of IL-4 and IL-13secretion, as well as increased levels of transcript for these cytokines." (PMID 21445234, 2011). "Conversely CD4+ T cell specific (LckcreIL-4Rα−/lox) IL-4Rα−/− mice are more susceptible than global IL-4Rα−/− mice to infection with L. mexicana, indicating a role for an IL-4/IL-13 responsive non CD4+ T cell population in early susceptibility." (PMID 21245915, 2011). "In contrast, Th2 responses, which are characterized by the production of IL-4, IL-13 and IL-10, result in susceptibility to infection." (PMID 21390155, 2011). "Our results suggest a regulatory effect of an IL4 gene promoter polymorphism on the intensity of parasite infections in a natural population of red-fronted lemurs, with a seemingly disadvantageous genotype represented in low frequencies." (PMID 21501512, 2011). "Because the most striking difference between the two groups was the level of IL-4 production, it was reasonable to associate IL-4 production with the increased susceptibility to experimental infection with the resistant isolate." (PMID 21390155, 2011). "Hosts who produce IFN-γ/IL-4/IL-5 in association with IL-10 present high levels of infection, proposing that the regulatory component is strongest to define the severity of pathology." (PMID 20544012, 2010). "Notably, CpG sites associated with Il4, Il13, Cd200, and Il1rl1 displayed the lowest methylation levels on Day 1 of infection, followed by an increase over time." (PMID 40170749, 2025). "The decrease in anti-inflammatory cytokines, such as IL-4 and IL-10, may be associated with better regulation of the immune system, resulting in greater control of infection and a balanced inflammatory response." (PMID 40367013, 2025). "Similarly, expression of IL-4, a cytokine associated with type 2 responses, has been shown to increase during experimental infection with BRSV, as well as M. bovis." (PMID 40703922, 2025). "Three cytokines, IL-4, IL-13, and G-CSF were also found to be associated with the immunoglobulin genes, and are known to be involved in the immunoglobulin response cascade during an infection." (PMID 37918965, 2024). "The results of in vivo experiments indicated that LincR-PPP2R5C deficiency led to an increase in the expression of IL-4 in the lung tissue of mice 21 days post infection, along with an increase in neutrophil infiltration in BALF and lung tissue and an increase in elastase content." (PMID 39287443, 2024).
infection (continued). "IL4 was negatively associated with the CSDD in the infection group, which could mean that as IL4 values increased throughout the weeks, the CSDD score decreased (and therefore became more normal or improved)." (PMID 37762523, 2023). "Recent findings have demonstrated that the development, aging, and elimination of neutrophils are accelerated in mice with a predisposition to interleukin-4 (IL-4)-mediated type 2 immunity, which, in turn, causes susceptibility to infection by several bacteria." (PMID 37386174, 2023). "Interestingly, the increased resistance of BALB/c mice to pH1N1 infection was associated with elevated IL-4 and IFN-γ production, suggesting that the Th1/Th2 cytokine paradigm is dependent on the infectious conditions." (PMID 37771584, 2023). "The IL4 -590C/T polymorphism might affect the ability of macrophages to inhibit infection caused by the bacillus." (PMID 37892223, 2023). "Nevertheless, IL-4 may act to limit this exacerbated response, increasing the susceptibility to the infection." (PMID 37915581, 2023). "For CRP, schoolchildren diagnosed with elevated CRP concentrations were more likely to have higher concentrations of IL-4, which might be an indicator for inflammation associated with infections." (PMID 37111135, 2023). "However, once Schistosoma eggs are produced at 5–6 weeks of infection, the host immune status dramatically shifts to a Th2 response, as shown by the increased production of Th2-associated cytokines IL-4, IL-5, IL-10, and IL-13." (PMID 35584107, 2022). "Furthermore, IL-4 and IL-13 inhibit the skin production of antimicrobial peptides and, thus, predispose AD skin to colonization and infection of Staphylococcus aureus, which further worsens skin inflammation and barrier defects." (PMID 34829844, 2021). "We measured the levels of IFN-gamma, IL-4, IL-10, IL-17A, IL-23, and IL-9 in the serum samples and PBMCs from the KO and WT mice at different stages of infection to conduct and extensive analysis of how USP21-deficient Tregs affect the resistance of mice to S. japonicum." (PMID 33628844, 2021). "These cause the production of the cytokines IL-4, IL-5, and IL-13, which in turn influence Immunoglobulin E (IgE) levels and eosinophilia, components of immune response associated with infection/re-infection resistance in schistosomiasis." (PMID 34185775, 2021). "Leakage of IL-4 into the systemic circulation could potentially increase the risk of infection, allergic reactions, and synovial hyperplasia." (PMID 33413614, 2021). "In addition, it has been shown that STAT6 (the signal transducer activated by the IL-4/IL-13 pathway) contains the rs324013 polymorphism, which was found in patients exhibiting higher levels of infection." (PMID 34281269, 2021). "This is consistent to literature reports that IL-4 knockout mice are susceptible to infection." (PMID 33644071, 2021). "Previous work on male genital schistosomiasis has shown that infection intensity, defined by seminal egg count, is strongly associated with elevated seminal cytokine concentrations including Th2 (IL-4), regulatory (IL-10), Th1 (IFN-γ) and pro-inflammatory (TNF-α) cytokines." (PMID 33737927, 2021). "Conversely, ITT sheep, which are resistant to F. gigantica and susceptible to F. hepatica, demonstrate a less dominating IL-4/IFNγ ratio and elevated IgG2 levels when displaying resistance against F. gigantica 10 weeks post-infection, compared to during a F. hepatica infection." (PMID 34207215, 2021). "Therefore, inhibition of lipolysis prior to infection leads M(IL-4) cells to become foamy, and is associated with an increase in Mtb intracellular growth." (PMID 33002063, 2020). "BALB/c is also highly susceptible to infection by L. major, with severe lesions and parasite-specific Th2 response with the enhanced expression of deactivating macrophage cytokines—particularly interleukin 4 (IL-4), interleukin 10 (IL-10), and transforming growth factor-β (TGF-β)." (PMID 32610603, 2020).
infection (continued). "In addition, the markedly impaired IL-4 production in CD1d KO mice resulted in an impaired MNV-S7-specific secretory IgA production after MNV-S7 infection which is associated with mucosal immunity." (PMID 31909227, 2020). "Importantly, neutralization of IL-4 produced at the time of infection was sufficient to provide protection in susceptible BALB/c hosts." (PMID 32948646, 2020). "However, IL-4Rα signalling appears to depend on the Leishmania species/sub-species initiating infection as L. major infection was also unchanged in IL-4/IL-4Rα-deficient mice." (PMID 33415318, 2020). "In some infections associated to Leishmania, IL-4 induction (as a Th2 cytokine) and increased the ARG activity with L-arginine metabolism in alternative activated macrophage cells (M2) play a significant role in the infection and parasite proliferation establishing." (PMID 31929528, 2020). "On the other hand, susceptibility/resistance to Leishmania parasite infection in BALB/c mice directly associates with the main dominance of IL-4 driven TH2 responses terminating infection or an IFN-γ dominated TH1 response that would result in healing along with parasite clearance." (PMID 31929528, 2020). "Interferon-gamma (IFN-γ) and tumor necrosis factor (TNF) -α and -β, from the Th1 profile, are known to be involved in the resistance and elimination of the parasites, while Th2 cytokines such as IL-4 and IL-10 are linked to susceptibility to infections by Leishmania." (PMID 31131262, 2019). "The non-significant levels of IL-4 observed in this study could possibly be attributed to the fact that the study was based on primary infection with P. berghei while IL-4 (a Th2 cytokine) has been associated with malarial immunity to reinfection." (PMID 31856836, 2019). "A hallmark of anti‐parasite type 2 immunity is the IL‐4 receptor (IL‐4Rα, essential for IL‐4 and IL‐13 downstream signaling) mediated activation of macrophages and the resulting M(IL‐4) activation phenotype, which has been associated with many crucial features of resistance to infection." (PMID 31267552, 2019). "For this reason, we employed the well-characterized BALB/c model of CL by L. amazonensis in which animals are susceptible to infection and develop chronic lesions in the presence of IL-4 and IL-10, in contrast with C57BL/6 mice, where these two Th2-characteristic cytokines seem to have no relevance." (PMID 31739549, 2019). "Susceptibility to infection was found to be IL-4 independent in BALB/c mice." (PMID 29953494, 2018). "The level of IL-4 splice variants in THP-1 cells increased after M. tb H37Rv infection." (PMID 29433383, 2018). "There is a credible immunological mechanism to explain this mutually exclusive phenomenon in that interferon gamma (IFN-γ) generated during infection down-regulates T-helper lymphocyte-2 (Th2) activity associated with the production of interleukin-4 (IL-4) which promotes IgE production." (PMID 29988421, 2018). "Thus, CCL7 deficiency appears to enhance the efficiency of early IL-4-producing effector T cell recruitment and/or retention at the infection site." (PMID 30671055, 2018). "For helminth infection in humans, the immune response during the early/acute phase of infection involves the induction of type 2-associated cytokines (IL-4, IL-5, IL-9, and IL-13) first by innate lymphocytes (ILC2) and later by effector antigen-specific polyfunctional CD4 T cells." (PMID 30416709, 2018). "For example, cellular prion protein has been implicated in the optimal production of T cell cytokines since T cells from cellular prion protein-deficient mice generate less IFNγ, IL-4, and IL-17 in response to TcR-stimulation and have altered responses to infection and autoantigens." (PMID 30533413, 2018).
infection (continued). "Thus, healing of CL in C57BL/6 mice is associated with a pronounced expansion of IFN-γ-secreting Th1 cells, whereas susceptibility of BALB/c mice is associated with a diminished IFN-γ, but increased IL-4-production in high-dose infection models." (PMID 29535708, 2018). "Moreover, a higher proportion of these CD4+ T cells from PE243-infected mice produced IFNγ and in a lesser extent IL-17, while infection caused a reduction of CD4+ T cells producing IL-4." (PMID 30087337, 2018). "Our results show that, at 40 days post-infection, there was an increase in the bacillary load in the liver and spleen associated to increased levels of IL-4, working memory deterioration, and changes in hippocampal morphology, including degeneration in the four subregions analyzed." (PMID 29899533, 2018). "Increased peripheral levels of IL-4 and IL-10 have also been described in Neospora caninum infected cattle, but are thought to be associated with a decreased ability of the host to control infections with coccidia." (PMID 29973271, 2018). "Immunity to infection with parasitic helminths such as the whipworm Trichuris muris is associated with a polarized type 2 cytokine response, with the production of IL-4, IL-5, and IL-13 by Th cells leading to mucus production, intestinal epithelial cell turnover, and worm expulsion." (PMID 28443098, 2017). "In an attempt to analyze if early after L. major inoculation, IL-4 secretion by keratinocytes could act in an autocrine way on these cells locally during the first days of infection, we generated mice genetically deficient in the IL-4Rα on keratinocytes." (PMID 29067025, 2017). "IL-4-null mice were as susceptible to infection as WT B6 mice." (PMID 28151989, 2017). "The coexistence of a mixed Th2/Th17 in reinfected mice with increased levels of IL-4 and IL-17A after each infection might also be associated to tissue injury and remodeling." (PMID 26814713, 2016). "Besides the high levels of IL-4 expected with this infection we also found elevated IL-10 levels associated with a downregulation of proinflammatory cytokines." (PMID 26090422, 2015). "First, while the administration of anti-IL-4 mAb to susceptible BALB/c mice prevented progressive uncontrolled infection of L. major and was paralleled by an up-regulation of IFN-γ production, the concurrent neutralization of this elevated IFN-γ did not abrogate or change the resistance phenotype." (PMID 26834705, 2015). "In this regard, the demonstration that infection of previously vaccinated mice with recombinant ECTV encoding IL-4 can completely overcome protective immunity and genetic resistance helped establish that over exuberant Th2-biased responses increase susceptibility to OPV infections." (PMID 25751266, 2015). "Combining treatments of TNFα and IFNγ, in analogy with the in vivo cytokine expression during day 14 and 19 post infection, further decreased the intensity of the complex-I and IV staining, but this loss was alleviated by simultaneous treatment with IL-4 (P < 0.01 vs P < 0.001)." (PMID 26481427, 2015). "Following infection with the parasite Trichuris muris, IL-27Rα KO mice exhibit accelerated expulsion of larval parasites associated with elevated production of parasite-specific IL-4, IL-5, and IL-13." (PMID 25633106, 2015). "Gamma interferon secreted by Th1 cells, is the most potent macrophage-activating cytokine leading to host resistance to infection with Leishmania parasites whereas IL-4 secreted by Th2 cells, is associated with down-modulation of IFN-γ -mediated macrophage activation." (PMID 24624248, 2014). "In addition, patients with ACL caused by L. amazonensis displayed lower levels of sera IL-4 and IL-17 when compared to infection by L. guyanensis." (PMID 25295285, 2014).